KCTD15 (potassium channel tetramerization domain containing 15)
Diseases named in the same sentence as KCTD15 in open-access papers (continued):
Sharing a sentence is not in itself a finding about the gene and the disease.
glioblastoma (1 paper, 2024). The most malignant astrocytic tumor (WHO grade IV). "Interestingly, data from GSE142825 showed that, in glioblastoma cells, KCTD15 mRNA expression was upregulated after YTHDF2 silencing, suggesting a negative regulatory role of YTHDF2 in KCTD15 mRNA stabilization." (PMID 38438714, 2024).
overnutrition (1 paper, 2023). An imbalanced nutritional status resulting from excessive intake of nutrients. "Relevant gene defects, such as melanocortin 4 receptor (MC4R), Src-homology-2 (SH2B1), and potassium channel tetramerization domain-containing 15 (KCTD15), were found to be associated with excessive eating behavior and overnutrition." (PMID 36902691, 2023).
cancer (11 papers, 2019 to 2025). A tumor composed of atypical neoplastic, often pleomorphic cells that invade other tissues. "KCTD15 showed strong positive correlations with hypoxia and invasion, highlighting its potential role in enhancing these cancer‐related functions." (PMID 40832836, 2025). "The controversial role of KCTD15 revealed in different types of cancers and the abnormal downregulation of KCTD15 in CRC specimens provoke us to explore KCTD15’s function in CRC." (PMID 38438714, 2024). "Here we find that KCTD15 exhibits lower expression in CRC tissues as compared to para-carcinoma tissues." (PMID 38438714, 2024). "Recently, a role for KCTD15 in cancer has been unveiled, based on its interaction with and stabilization of KCASH2KCTD21 protein." (PMID 34001146, 2021). "However, the associations of KCTD2, KCTD15, and KCTD21 with cancer progression remain underexplored, making our findings novel and significant." (PMID 40832836, 2025). "Emerging evidence has highlighted the significance of various gene families in cancer progression, including the KCTD family, comprising genes, including KCTD2, KCTD5, KCTD9, KCTD10, KCTD12, KCTD15, KCTD16, and KCTD21." (PMID 40832836, 2025). "KCTD15 belongs to the KCTD family and plays an inconsistent role in the carcinogenesis of different cancers." (PMID 38438714, 2024). "Although KCTD1 shares several features and biological functions with KCTD15, including the inability to bind to Cul3, its role in cancer has still not been intensively investigated." (PMID 34001146, 2021). "In addition to proteins known to directly bind REN, such as Cul3, RBX1, and KCTD15, we recovered various potential REN interactors including SALL4, a cell stemness regulator aberrantly activated in several types of human cancers." (PMID 38062245, 2024). "Up to date there are no available strategies to positively regulate KCTD15 expression in cancer, though further studies on its transcriptional modulation may uncover potential pharmacological modulators." (PMID 31685809, 2019). "However, unlike KCTD15, it has been shown that KCTD1 is involved in proteasomal degradation processes, by complexing with other E3-ubiquitine ligases, through which it participates in negative regulation of pathways which are aberrantly activated in many human cancers." (PMID 34001146, 2021).
tumor (6 papers, 2019 to 2024). "Results of Western Blot demonstrated that the expression of KCTD15 in tumor tissues was successfully induced." (PMID 38438714, 2024). "Meanwhile, apoptotic cells within tumor tissues were detected via TUNEL staining, and the results indicated that KCTD15 overexpression induced apoptosis in tumor tissues." (PMID 38438714, 2024). "The effects of KCTD15 on tumor growth were further verified by the detection of Ki67 expression via Western Blot and IHC staining." (PMID 38438714, 2024). "The results showed that the induction of KCTD15 expression significantly inhibited tumor growth." (PMID 38438714, 2024). "To verify the effect of KCTD15 on this tumor model, we overexpressed KCTD15 in DAOY cells." (PMID 31685809, 2019). "In particular, KCTD15 expression was evaluated in Luminal A, Luminal B, and HER2+ tumor tissues extracted from 10 patients and compared with tissues obtained from healthy subjects." (PMID 35328144, 2022). "Different expression of KCTD15 had no significant impact on age, gender, tumor size, depth of tumor invasion, and differentiation." (PMID 38438714, 2024). "The expression levels of CD44, CCND3, NCALD, MACF1 and KCTD15 were downregulated in the vast majority of LUAD histological subtypes compared with in normal samples; additionally, they were differentially expressed according to tumor stage and nodal metastasis status." (PMID 33281971, 2021). "Furthermore, the expression levels of CD44, CCND3, NCALD, MACF1 and KCTD15 were downregulated in the vast majority of LUAD histological subtypes compared with in normal samples, and they were differentially expressed according to tumor stage and nodal metastasis status." (PMID 33281971, 2021).
KCTD15 also shares sentences with these, for which no sentence is quoted: autism (2 papers); Insulin resistance (2); schizophrenia (2); anhidrosis (1); Anorexia (1); bipolar disorder (1); childhood leukemia (1); congenital heart disease (1); cyst (1); diabetes (1); frontonasal dysplasia (1); Hypodontia (1); liver diseases (1); lymphoid leukemia (1); movement disorder (1); oligodendroglioma (1).